POT1 (protection of telomeres 1)
Diseases named in the same sentence as POT1 in open-access papers (continued):
Sharing a sentence is not in itself a finding about the gene and the disease.
cancer (continued). "TPP1 heterodimerizes with POT1 but there are no results about the correlation between TPP1 levels and telomere length in cancer samples." (PMID 24260532, 2013).
tumor (39 papers, 2012 to 2026). "There are no published guidelines for the surveillance of individuals with a POT1 tumor predisposition." (PMID 38540414, 2024). "The aim of the present study was to assess the prevalence of POT1 mutations in cDLBCL and to elucidate the role of such gene in the pathogenesis of this tumor." (PMID 36016811, 2022). "For example, the proportion of mutant samples affected by intronic mutations in tumour suppressors ranged up to 50% (e.g., POT1)." (PMID 33420369, 2021). "Tumor telomere length was significantly longer in cleanup workers and was associated with the POT1 mutation and survival." (PMID 31480731, 2019). "The same POT1 variant was identified in both tumor tissues in a heterozygous state." (PMID 42232556, 2026). "Therefore, we cannot formally establish a causal relationship between these tumours and the presence of the POT1 PV." (PMID 38839987, 2024). "Looking for unique features of POT1-associated tumors may provide insights regarding tumor behavior and, perhaps, clues for diagnosis." (PMID 38540414, 2024). "The wide-tumor spectrum shown in these LFL families made this POT1 mutation especially interesting since it could be at the origin of very different tumor types." (PMID 35727838, 2022). "This could be explained by an inherited epigenetic effect of the POT1 variant or by other genetic or environmental factors that contribute to tumor development." (PMID 35323213, 2022). "The long somatic telomeres caused by human germline POT1 mutations could impede the ability of senescence to suppress tumor development but may also affect DNA damage signaling and recombination at telomeres." (PMID 35323213, 2022). "Furthermore, the somatic molecular genetic makeup of the myeloid blast cells displayed an atypical monosomy 7q- with derivative chromosome 7, potentially leading to a loss of the remaining POT1 wild-type (WT) allele (located on chromosome 7q) in the tumor." (PMID 34769003, 2021). "So, it is tempting to speculate that telomere elongation induced by this mutation in POT1 may constitute the underlying molecular mechanism favouring tumour incidence." (PMID 26403419, 2015). "Since some of the reported tumours are also common in the general population, a clear definition of POT1 tumour spectrum is hard to make." (PMID 38839987, 2024). "The impact of alterations in RAD51B, GID4, and POT1 on telomeric content was proportional to tumor purity, but in samples WT for known TMM genes, telomeric content was not impacted by tumor purity." (PMID 37709802, 2023). "Ectopic POT1 expression in GC cells suppressed cell viability and induced apoptosis, suggesting that it functions as a tumor suppressor in GC." (PMID 31534549, 2019). "Tumor telomere length was significantly longer in UR-CLL than in UN-CLL (p = 0.009) and was associated with the POT1 mutation and survival." (PMID 29720177, 2018). "Many studies have indicated that POT1 gene dysfunction in malignant human tumor cells induces senescence and apoptosis." (PMID 29546066, 2018). "For instance, transcription factors pleiotropically linked to stem cell migration (e.g. KITLG), telomere maintenance (e.g. POT1) and also tumor suppressors (e.g. TSC2)." (PMID 27264734, 2016). "A second conclusion from these data are that the expressions of TERT, TRF2, TRF1, TIN2, and POT1 can be regulated by factors presumed to be at the tumor site, including mediators of stress (glucocorticoids) and inflammation (TNF-α)." (PMID 23342266, 2012). "It has previously been shown that the expression of the telomere-associated protein POT1, and possibly TRF2, mRNA decreases in tumor tissue compared with corresponding normal tissue and is associated with disease progression." (PMID 23342266, 2012). "Most of the tumours related to POT1 PV are diagnosed in adulthood." (PMID 38839987, 2024).
tumor (continued). "POT1-TPD is treated according to the standard of care for each type of tumour." (PMID 38839987, 2024). "In addition, the shelterin‐complex genes: TINF2 and POT1 exhibited a twofold increased number of expression outliers among clinically aggressive tumours." (PMID 35979662, 2022). "POT1 mis-splicing was recurrently observed in two tumour samples." (PMID 33420369, 2021). "Biofunctional work revealed that POT1 functions as a tumor suppressor." (PMID 31534549, 2019). "The effect of gender on the expression of the studied genes revealed that for ATR females had two-fold higher expression compared to males, whereas POT1 was expressed at a significantly higher level in the tumor tissue relative to adjacent mucosa only in the male patients." (PMID 29870526, 2018). "However, recent studies have shown that the repression of POT1 expression can result in tumor progression." (PMID 29546066, 2018). "Therefore, the development of POT1 and telomerase inhibitors may be a potential approach to enhance radiosensitivity in these tumours." (PMID 38839987, 2024). "Once SerRS enters the nucleus, it can directly bind telomeric DNA repeats and tether more POT1 protein on telomeres, which prevents the engagement of telomerase, resulting in progressive telomere shortening and cellular senescence, thus leading to tumor suppression." (PMID 31815007, 2019). "However, no additional POT1 variants were found in any of the tumor samples." (PMID 36387164, 2022). "One exception was increased levels of POT1 mRNA correlated linearly with increased tumor size (P = 0.002, data not shown)." (PMID 23342266, 2012). "The aim of the present study was to extend POT1 genetic analysis to an independent cohort of dogs with DLBCL treated with chemo-immunotherapy in order to further investigate the prognostic significance and the role of such gene in the pathogenesis of this tumor." (PMID 36016811, 2022).
infection (7 papers, 2017 to 2025). The state of being infected such as from the introduction of a foreign agent such as serum, vaccine, antigenic substance or organism. "Our results show that with the exception of TEV‐CAA10, the eIF4E1P69T/ET protein behaves similarly to the natural resistant pot1‐encoded protein that appears to make the SleIF4E2 unavailable to the potyvirus infection by a yet unknown mechanism." (PMID 36715107, 2023). "We co-expressed TRF2, TIN2, TPP1, and POT1 by simultaneous infection of cells with individual shelterin baculoviruses." (PMID 29057866, 2017). "However, POT1-treated plants before infection (T3) or before + after (T4) exhibited higher expression levels with 4.823- and 5.656-fold change, respectively." (PMID 32999301, 2020). "The POT1 gene was knocked down by infection with POT1 lenti-shRNA." (PMID 29546066, 2018). "The endogenous POT1 in these cell lines was reduced by infection with shPOT1." (PMID 28393830, 2017). "Finally, POT1, MFE2, and enoyl CoA hydratase CNAG_04531 are required for full fitness during infection." (PMID 41394754, 2025).
hematologic malignancies (5 papers, 2018 to 2025). "POT1, a gene associated with telomere maintenance, was mutated in 3 of the 84 patients with hematological disorders." (PMID 40202536, 2025). "Germline POT1 variants are associated with clonal hematopoiesis, T cell clonality, and various solid and hematological malignancies." (PMID 40202536, 2025). "Regarding haematological diseases, it is well documented that POT1 mutations increase CLL risk." (PMID 38839987, 2024). "Moreover, a recent study showed the relationship between long telomeres due to POT1 mutations and familial clonal haematopoiesis syndrome, which broadens the spectrum of predisposition to malignant haematological diseases." (PMID 38839987, 2024). "Future studies will be important to investigate the link between specific POT1 PV and the incidence of haematological diseases." (PMID 38839987, 2024). "Further genes simultaneously affected by sCNAs and SNVs/indels, included POT1, JAK1, and PCM1, which are all linked to hematologic malignancies." (PMID 29449575, 2018).
adenocarcinoma (1 paper, 2024). A common cancer characterized by the presence of malignant glandular cells. "The gene expression levels of hTERT, ISG15, TRF2, and POT1 were analyzed by qPCR in PC9 cells, an NSCLC adenocarcinoma cell line, and human lung fibroblast (HLF) cells." (PMID 38891017, 2024).
benign tumors (1 paper, 2025). "POT1 is involved in telomere maintenance and gPVs in POT1 predispose to development of multiple malignant and benign tumors (OMIM: 615848)." (PMID 39979679, 2025).
blood cancers (1 paper, 2021). "In particular, a telomere maintenance gene, POT1, was recurrently mis-spliced by deep intronic mutations in blood cancers." (PMID 33420369, 2021).
POT1 also shares sentences with these, for which no sentence is quoted: diffuse large B-cell lymphoma (3 papers); dyskeratosis congenita (3); colorectal adenoma (2); genetic diseases (2); idiopathic pulmonary fibrosis (2); leiomyosarcoma (2); leukaemia (2); papillary thyroid cancer (2); soft tissue sarcoma (2); splenic marginal zone lymphoma (2); squamous cell carcinoma (2); aplastic anemia (1); autism (1); autism spectrum disorder (1); autoimmune thyroid disease (1); basal cell carcinoma (1); cervical cancer (1); Cirrhosis (1); colon cancer (1); Cowden syndrome (1); cutaneous squamous cell carcinoma (1); endometritis (1); Ewing sarcoma (1); familial colorectal cancer (1); gastrointestinal stromal tumor (1); hereditary medullary thyroid carcinoma (1); hypothyroidism (1); laryngeal carcinoma (1); lymphoproliferative syndrome (1); mast cell tumors (1).
A further 16 diseases each share a sentence with POT1 in 1 paper.